HIF1A (hypoxia inducible factor 1 subunit alpha)
Diseases named in the same sentence as HIF1A in open-access papers (continued):
Sharing a sentence is not in itself a finding about the gene and the disease.
infection (continued). "Importantly, when the infection establishes with severe prolonged hypoxic conditions, here characterized as long-term hypoxia (24 h), MCs adapt to hypoxia by stabilizing HIF-1α on protein level." (PMID 28553287, 2017). "Taken together, these findings make it highly unlikely that we were selectively eliminating HIF1α expressing cells following infection with H. pylori and therefore, that the effects observed after 24 h were not linked to induction of HIF-1α upon H. pylori infection." (PMID 28401064, 2017). "While HIF1α stabilization by hypoxia can explain increased FcγRIIA expression, it alone is insufficient for enhanced infection as chemical stabilization of HIF1α in cells cultured at atmospheric O2 levels showed increased FcγRIIA expression but not viral entry." (PMID 28320741, 2017). "Both WT and HIF-1α KO mice exhibited increases in spleen weight after infection." (PMID 29222473, 2017). "Since our results showed an increase in the nuclear localization of HIF-1α and an increase in the reporter activity after 8 h of infection by H. pylori, we next evaluated whether some of the known target genes of HIF-1α were induced by H. pylori infection." (PMID 28401064, 2017). "Interestingly, the level of hypoxia-induced accumulation of HIF-1α was significantly reduced in hypoxic Saos-2 cells following the infection." (PMID 27902314, 2016). "Mice lacking myeloid HIF-1α showed higher susceptibility to infection with Streptococcus pyogenes and decreased neutrophil production of granule proteases and the murine cathelicidin peptide CRAMP31." (PMID 27633343, 2016). "HIF-1α is induced by pro-inflammatory cytokines, growth factors, and a broad range of infections, and its induction is a general component of the host response to infection." (PMID 27148269, 2016). "M.tb caused significant accumulation of HIF-1α in direct infection and via a networking effect even in the absence of hypoxia, with a synergistic increase in HIF-1α expression in hypoxia or following treatment with DMOG." (PMID 27245780, 2016). "In addition, the hypoxic environment characteristic of the site of infection, resulting from an elevated oxygen consumption by immune cells 44, 45, triggers an increased stabilisation of HIF‐1α protein by reduction of prolyl hydroxylase activity." (PMID 26513405, 2016). "Similarly, quantitative immunofluorescence analysis shows a significant increase of the cytoplasmic HIF-1α signals in A549 exposed to the infection of the Kp strains (p<0.001)." (PMID 26812644, 2016). "HIF-1α was progressively expressed in DCs during the first week of infection." (PMID 26046638, 2015). "However, the difficulty of making sense of PTM patterns is nicely illustrated in this case: HIF1A pops up 17 times in the candidate top-5 lists, 9 times in spots that are up regulated in response to infection, 8 times in down regulated ones." (PMID 25627479, 2015). "Given the need of myeloid cells to adapt to hypoxic and inflamed microenvironments that develop during infection, the hypoxia-inducible factor 1-alpha (HIF-1α) has been found to be essentially required for chemokine production and maintenance of neutrophil numbers in the lungs of infected animals." (PMID 25999936, 2015). "As with inflammatory processes, HIF-1α has activating effects on leukocytes during infection." (PMID 26512123, 2015). "Considering that early following fungal challenge there is precedence for the requirement of neutrophils and inflammatory monocytes in terms of infection outcome, we next sought to determine how HIF1α is involved in the neutrophil response following fungal challenge." (PMID 25255025, 2014). "The increase in susceptibility of the myeloid deficient HIF1α mice to A. fumigatus was in part due to decreased early production of the chemokine CXCL1 (KC) and increased neutrophil apoptosis at the site of infection, resulting in decreased neutrophil numbers in the lung." (PMID 25255025, 2014).
infection (continued). "However the HA-HIF-1α APAS protein accumulated to similar levels in both mock and MRV infected cells, suggesting that the PAS domains of HIF-1α are necessary for MRV infection induced degradation of HIF-1α." (PMID 24504474, 2014). "The emerging role of HIF-1α in mucosal barrier function may also be an important protective mechanisms in the face of the infection-induced increase in permeability." (PMID 24465430, 2014). "The significance of this observation is currently unknown, however we noted that at least one interferon-inducible cellular factor known to transactivate the ORF73/LANA promoter was sharply upregulated at 4 h post infection (HIF1A)." (PMID 25033267, 2014). "Taken together, in a healthy immune competent murine lung, HIF1α is stabilized in response to A. fumigatus pulmonary challenge, suggesting an important role for this protein in resistance to pulmonary fungal growth and subsequent infection." (PMID 25255025, 2014). "As control of metabolism and production of energy in inflammatory, low oxygen infection sites is dependent upon HIF1α, it is in accord that innate inflammatory responses required for clearing and preventing infection are also tied to this important transcriptional regulator." (PMID 25255025, 2014). "Stabilization of HIF-1α during the pathogenesis of mycobacterial infection may represent a therapeutic opportunity to re-arm leukocytes and to inhibit further infection." (PMID 24367256, 2013). "Infection of mice with Y. enterocolitica led to functional activation of HIF1A in Peyer's patches." (PMID 24086109, 2013). "In order to check if the observed up-regulation of miR-210 was specifically under HIF-1α control, we used siRNA to silence this TF before infection (HIF-1α silencing leads to a 90% decrease in HIF-1α protein abundance; Tiffin and Sysco Consortium, submitted paper)." (PMID 24098824, 2013). "Therefore, to understand the mechanism of action of early Hif-1α stabilization, we focused on the role of bacterial killing by the leukocytes during early stage infection." (PMID 24367256, 2013). "This led us to hypothesize that LD-infection also might result into HIF-1α stabilization in host cells." (PMID 22701652, 2012). "To verify this, we tested HIF-1α protein stabilization during LD infection." (PMID 22701652, 2012). "An increase in HIF-1α mRNA was also observed by real-time RT-PCR in macrophages isolated from LD-infected mice confirming this mechanism is also operative during in vivo infection." (PMID 22701652, 2012). "C. pneumoniae has been shown to directly disrupt function of HIF-1a during infection of epithelial cells in vitro, which indicates that this lung pathogen may attempt to counteract the effects of A2b expression in actively infected cells." (PMID 20011598, 2009). "However, more recently many studies have also demonstrated a role of HIF-1α in the transcriptional coordination during inflammation and infection." (PMID 18839041, 2008). "In addition, recent studies have revealed that during infections with human pathogens, HIF-1α is activated." (PMID 18839041, 2008). "However, studies that are more recent have identified an additional role of HIF-1α as transcriptional regulator of inflammation and infection." (PMID 18839041, 2008). "In addition, recent studies identified a role for HIF-1α as transcriptional regulator during inflammation or infection." (PMID 18839041, 2008). "Moreover, studies of HIF-1α during infection with enterobacteriaceae revealed hypoxia-independent activation by bacterial siderophores." (PMID 18839041, 2008). "Based on studies showing that respiratory syncytial virus (RSV) is among the most potent biological stimuli to induce an inflammatory milieu, we hypothesized a role of HIF-1α as transcriptional regulator during infections with RSV." (PMID 18839041, 2008).
infection (continued). "In summary, we unraveled a novel mechanism of inflammasome activation mediated by GBP1 and HIF‐1α, which orchestrates differential immune response in macrophages and in vivo upon infection with Mtb strains that cause a progressive or nonprogressive infection." (PMID 41287823, 2025). "However, modulation of HIF‐1α activity at the onset of infection may impair early T‐cell differentiation in the lymph nodes." (PMID 40815083, 2025). "However, it is still not fully understood whether the induction of HIF-1α during infection confers a beneficial protective response or contributes to disease progression and host damage." (PMID 40731804, 2025). "However, it remains unclear whether HIF-1α activation is protective or harmful to the host, as its effects may vary depending on the context of the infection." (PMID 40731804, 2025). "Therefore, temporally controlled modulation of HIF‐1α, particularly at later stages of infection, may be a more appropriate strategy for evaluating tissue‐resident T‐cell responses." (PMID 40815083, 2025). "Although prior work has shown that HIF1a promotes leukocyte proinflammatory activity and bacterial clearance in models of planktonic infection, we explored whether it may be detrimental in the context of biofilm infection by augmenting G-MDSC glycolytic activity." (PMID 38421730, 2024). "Importantly, under hypoxic conditions the infection with E. coli induced a higher HIF1α protein level at 4 and 24 h post-infection compared to the infection with viable C. burnetii, indicating that C. burnetii might be able to restrict HIF1α accumulation." (PMID 35755850, 2022). "Mice with HIF-1α-deficient myeloid cells displayed increased lung bacterial burden compared to WT mice 120 days post-infection and when infected with hypervirulent M.tb, although this was not seen at lower dose infections." (PMID 36297211, 2022). "Also, MIR210HG was upregulated in our infection models and was described to act together with HIF1α to promote glycolysis during cancer, revealing that lncRNAs may be involved in regulating metabolic pathways." (PMID 36685903, 2022). "The literature reported that mice deficient in HIF-1α in their myeloid cells reduced bactericidal activity and could not limit the systemic spread of infection." (PMID 34898382, 2022). "Moreover, at an MOI of 10, HIF1α stabilization decreases during the course of the infection." (PMID 35755850, 2022). "Therefore, special care should be taken when considering the use of HIF1α inhibitors as they may compromise NK cell function under certain conditions such as pathogen infection." (PMID 34396954, 2021). "However, boosting of HIF1α activity to fight infections bears risks as well." (PMID 33125509, 2021). "Notably, HIF-1α also broadly promotes the infection of other viruses." (PMID 34408131, 2021). "Additionally, the infection efficiency of YAP/HIF-1α overexpression or knockdown in the TH17 cells was evaluated and confirmed by means of RT-qPCR and Western blot analysis, where sh-YAP-1 and sh-HIF-1α-1 exhibited superior efficiency, and were thus used for further experimentation (p < 0.05)." (PMID 33980319, 2021). "HIF1α deficiency in myeloid cells did not affect bacterial outgrowth within 12 hours of infection." (PMID 34393650, 2021). "Thus, our results indicate that the enhanced NOS2 expression, NO production and the inflammatory profile promoted by HIF-1α may support the control of B. abortus during the early phase of infection." (PMID 33989349, 2021). "The bactericidal properties of HIF‐1α stabilisation have now been moved into clinical settings, with promising results from CoCl2 containing bandages, that not only prevented bacterial survival and growth, but also promoted wound healing both in vitro and in vivo in a mouse infection model." (PMID 32633061, 2020).
infection (continued). "Furthermore, DANCR has been shown to affect HIF1a’s stability in malignancy, suggesting that the mechanism controlling this interaction may likewise be operational in other contexts, including infection control." (PMID 33163005, 2020). "We presume that at the early stage of infection, T. gondii stimulates pathogen sensors or receptors on host cell surface by directly binding or indirectly through its secretory molecules (e.g., ESAs) which will mediate the series activation of HO-1 and HIF-1α to initiate VEGF expression." (PMID 32432052, 2020). "Importantly, mTOR suppresses factor inhibiting HIF-1 (FIH-1), a negative regulator of HIF-1α57, and FIH-1 may represent one central node congregating mTOR and HIF-1α signaling towards the activation of glycolysis in response to infection." (PMID 32385235, 2020). "Also, this type of drug may be used for treating NDV, because infection with this virus downregulates HIF-1α stabilization, and therefore the activation of this transcription factor may have an antiviral effect." (PMID 33135539, 2020). "We further demonstrate that both Hif1α and Ldh are crucial not only for full macrophage activation, but also for the bactericidal function of the immune cells, with the rearrangement of macrophage metabolism towards AG being essential for resistance to infection and host survival." (PMID 31609200, 2019). "HIF-1α-mediated Warburg effect likely contributes to protective immune responses at the site of infection early in disease but may lead to injurious necrosis and pathology during a prolonged infection." (PMID 30930886, 2019). "Additionally, restricting iron availability in host immune cells may also serve to fight Mtb infection by stabilizing HIF1α to enhance important inflammatory and metabolic processes central to eradicating the infection." (PMID 30374347, 2018). "Furthermore, HIF1α acts a positive feedback mediator during this process and acts to sustain the role of IFNγ in macrophage activation, helping to control and restrain the infection." (PMID 30374347, 2018). "Thus, HIF-1α emerges as an unsuspected linker between cell cycle progression/proliferation and cell cycle arrest/apoptosis, two seemingly contradictory effects observed in gastric cells following infection with H. pylori." (PMID 28401064, 2017). "By dissociating siderophore secretion from bacterial growth, we could directly compare levels of proinflammatory cytokine secretion, bacterial dissemination, and HIF-1α stabilization in response to infection with isogenic siderophore synthesis mutants at equivalent bacterial numbers." (PMID 27624128, 2016). "Infection with WT K. pneumoniae did not cause HIF-1α-dependent differences in lung bacterial load." (PMID 27624128, 2016). "HIF-1α is also stabilized by a wide range of pathogens, and because infections can modulate several signalling pathways, HIF-1α stabilization might contribute to different metabolic outcomes in a context-dependent manner." (PMID 25351724, 2015). "Moreover, hypoxia may modulate innate immune response in the setting of an infection or inflammation by transcriptional regulation of TLRs expression and function via HIF-1α." (PMID 26491664, 2015). "Moreover, these mice had a significantly lower parasite burden in the spleen, suggesting that induction of HIF-1α may represent an immune evasive mechanism adopted by Leishmania parasites to establish persistent infections." (PMID 26046638, 2015). "To extend these findings, we examined whether HIF-la protein activity was similarly diminished by MRV infection by measuring transcription from a HIF-1α-dependent firefly luciferase plasmid (pHRE-Luc) transfected into mock- and MRV-infected DU145 cells grown in normoxic and hypoxic conditions." (PMID 24504474, 2014).
infection (continued). "In order to determine whether Hif-1α was induced in liver fibrotic tissues as liver was injured by infection, we firstly detected Hif-1α expression in liver tissues of Schistosomajaponicum infected mice, which is recognized as a good model for infectious liver fibrosis." (PMID 24040163, 2013). "Therefore, we hypothesized that changes in metabolic supply and demand ratios during RSV infection may accompany RSF-infection and RSV-associated tissue hypoxia could lead to HIF-1α activation." (PMID 18839041, 2008). "We now describe that the suppressed PHD2D4E;C127S, and resulting elevated HIF1α, and decreased the IFN synthesis in these mutant cells in normoxia upon infection." (PMID 40570045, 2025). "Baricitinib partially reversed pro-apoptotic changes, suppressing HIF-1a and cleaved Caspase-3, but further reduced Survivin and HTRA2, indicating selective modulation of apoptosis during infection." (PMID 41255708, 2025). "In Drosophila, both genetic and infection-induced activation of Toll and IMD signaling can induce the expression of HIF-1α in immune cells under aerobic conditions." (PMID 39859663, 2025). "Other inducers include hypoxia through HIF1A/HIF-1α, oxidative stress via NFE2L2/NRF2 activation, protein misfolding, and infection through pattern recognition receptors (PRRs)." (PMID 40910070, 2025). "This infection upregulated certain gene expressions, such as ATP5PF, ATP6, COX1, MT-ND5, CYTB, and HIF-1α and downregulated CACNA1B and RYR3 expression." (PMID 41157602, 2025). "Pathogen interaction studies demonstrate that Mycobacterium tuberculosis-infected DCs upregulate HIF-1α-driven aerobic glycolysis via TLR2-dependent mechanisms, a metabolic reprogramming event critical for DC migratory responses during infection." (PMID 40791591, 2025). "Our observations suggest that Mtb‐strain‐dependent differences in regulating the inflammasome activation by GBPs and HIF‐1α contribute to the difference in the pulmonary disease pathology between HN878 and CDC1551 infections in vivo and in vitro." (PMID 41287823, 2025). "Differential expression analysis in this dataset showed a significant upregulation of four core genes (CCL5, PTGS2, HIF1A, and CLEC4E) in the infection group." (PMID 41039310, 2025). "We report a novel mechanism of inflammasome activation mediated by GBP1 and HIF‐1α, which orchestrates differential inflammasome activation and inflammatory response in macrophages and in vivo upon infection with Mtb strains that cause a progressive or nonprogressive infection." (PMID 41287823, 2025). "A significant downregulation of HIF1A, NLRP3, GBP1 and ASC, and upregulation of IL1B was observed in HIF1A‐KD macrophages, while downregulation of ASC was noted in GBP1‐KD macrophages infected with HN878, compared with CDC1551 infection." (PMID 41287823, 2025). "During S. marcescens infection in Drosophila, IMD/inhibitor of NF-κB kinase (IKK)/Relish signaling induces HIF-1α expression, and knockout of HIF-1α increases mortality during infection." (PMID 39859663, 2025). "Acute hypoxia stress induces a significant up-regulation of HIF-1α and then which induces YAP (Yki homolog in mammal), while pathogen infection inhibits the expression of Yki." (PMID 39664389, 2024). "Both the knockdown of HIF-1α and treatment of the myocardial cell with QFPDD significantly reversed the increased inflammatory factors during infection." (PMID 38476329, 2024). "Most HIF-1α translocated from the cytoplasm to the nucleus in RSV-infected cells 12 and 24 h after infection." (PMID 37796013, 2023). "HIF-1α stability potentiates Toxoplasma infection and vice versa by preventing HIF-1α prolyl hydroxylation.Infection significantly decreases PHD2 abundance, which is the key prolyl hydroxylase for regulating HIF-1 α." (PMID 37600803, 2023). "In particular, we found increased TGF-β1, FGF23, NGAL, IL-18, HIF1-α, TLR2, YKL-40, and B2M mRNA levels long-term post MHV-1 infection." (PMID 37626956, 2023).